EMP1 (epithelial membrane protein 1)
Diseases named in the same sentence as EMP1 in open-access papers (continued):
Sharing a sentence is not in itself a finding about the gene and the disease.
ductal carcinomas (1 paper, 2007). "Seven differentially expressed genes (KRT5, KRT6 and KRT17 between tumor and normal cells, CDH1, EMP1, DDR1 and DVL1 between lobular and ductal carcinomas) were verified by immunohistochemical detection of proteins on TMA slides comprising of cores from 119 cases." (PMID 17389037, 2007). "Epithelial membrane protein 1 (EMP1), discoidin domain receptor 1 (DDR1) and human homolog of the Drosophila dishevelled gene (DVL1) were found by pairwise comparison analysis to be differentially expressed between lobular and ductal carcinomas." (PMID 17389037, 2007).
ischemia (1 paper, 2022). A hypoperfusion of the BLOOD through an organ or tissue caused by a PATHOLOGIC CONSTRICTION or obstruction of its BLOOD VESSELS, or an absence of BLOOD CIRCULATION. "We found that endothelial markers (Angptl4), and pericyte marker (Cyp1b1, Emp1, S1pr3, Serping1, and Cxcl1) were upregulated in prolonged ischemia." (PMID 35154109, 2022).
liver cirrhosis (1 paper, 2023). "Meanwhile, in GSE73499 following 3, 6, and 9 weeks of CCl4 administration, the expression of the Emp1 gene was also significantly upregulated in the rat liver cirrhosis model (log2FC = 1.117, P = 6.13 × 10−3)." (PMID 37008256, 2023).
liver disease (1 paper, 2025). "Although EMP1 is an adhesion protein implicated in tumor invasion and migration via cell adhesion and transmembrane trafficking, its role in non-oncological contexts such as liver disease remains poorly understood." (PMID 41284206, 2025).
metastatic cancers (1 paper, 2018). A carcinoma which has spread from the original site of growth to another anatomic site. "With respect to clinical implications, development of an inhibitory antibody to specifically target EMP1 to infer the potential of this molecule may be challenging because of the high expression of EMP1 in pro-metastatic cancers." (PMID 29867202, 2018). "The PCR results also showed that the expression of EMP1 was strongly increased in highly malignant and metastatic cancer cells, such as PC3 and MDA-MB-231 cells, suggesting a pro-metastatic function of EMP1." (PMID 29867202, 2018).
metastatic colorectal cancer (1 paper, 2012). "EMP1 is involved in the EGFR signaling pathway with an important role in cell proliferation and epithelial cell differentiation and it is considered important in metastatic colorectal cancer." (PMID 23119007, 2012).
osteosarcoma (1 paper, 2024). A usually aggressive malignant bone-forming mesenchymal neoplasm, predominantly affecting adolescents and young adults. "Elevated EMP1 expression in osteosarcoma tissues is closely associated with lymphatic and distant metastasis, stimulating malignant progression via the IRX2/MMP9 axis." (PMID 40612666, 2024).
prostate tumor (1 paper, 2018). "Immunohistochemistry showed strong EMP1-positive staining in the prostate tumor areas, especially at the invasive front, of the higher Gleason score samples compared with the lower Gleason score samples." (PMID 29867202, 2018).
sarcoma (1 paper, 2021). A usually aggressive malignant neoplasm of the soft tissue or bone. "We have shown that established Rh30 and RD sarcoma cell lines cultured in the presence of the tested PRMT inhibitors have decreased expression of TNC, NRP1, MYOF, EMP1, OLFML3 and CCND1 and increased expression of the GADD45G gene." (PMID 34360791, 2021).
Sepsis (1 paper, 2025). Sepsis is defined as life-threatening organ dysfunction caused by a dysregulated host response to infection. "Dot plot visualization further confirmed these trends at the gene level, with C3, SERPING1, and HLA-A/B/C being notably upregulated in Astrocyte 2 under sepsis conditions, while EMP1, CLCF1, and PTGS2—representing A2 features—were similarly elevated." (PMID 41030458, 2025).
tumor (65 papers, 2003 to 2025). "Several studies have shown that EMP1 is involved in the biological behavior of tumor cells through tumor-associated signaling pathways." (PMID 41458590, 2025). "Loss of EMP1 in these contexts is associated with higher tumor grade, advanced stage, and poor prognosis." (PMID 41465326, 2025). "Cell co-culture assays, xenograft tumor experiments, loss-of-function, gain-of-function, RNA sequencing studies, and rescue assays were performed to confirm the role of EMP1 in CAF infiltration in vitro and in vivo." (PMID 40016223, 2025). "Epithelial Membrane Protein 1 (EMP1) was identified to be the key gene indicative of tumor M1/M2 ratio, and higher EMP1 expression was associated with poor prognosis in many tumors." (PMID 38542388, 2024). "Comparative analysis between high and low EMP1-expressing tumor cells revealed overexpression of genes encoding transcription factors and surface proteins in the former, predominantly enriched in oxidative phosphorylation pathways." (PMID 40612666, 2024). "Our study, using both in vivo and in vitro validations, elucidated that the aging-associated factor EMP1 in PC modulates tumor proliferation, invasion, and metastasis via the PI3K/AKT signaling pathway." (PMID 40612666, 2024). "CRC cells with a high expression of EMP1 can be more aggressive and cause tumor metastasis and recurrence in CRC patients." (PMID 38818308, 2024). "CIBERSORT, ESTIMATE, and immune checkpoint genes were used to assess the association between EMP1 expression and tumor microenvironment features." (PMID 36708070, 2023). "High EMP1 level, contributing to high FerrScore, was associated with advanced T stage, high grade tumor and lower CR rate." (PMID 35641509, 2022). "During primary lung tumor sample analyses, we found that lower expression of EMP1 were significantly associated with increased tumor size." (PMID 33799364, 2021). "On the other hand, reduced protein expression of EMP1 is associated with a poor survival rate, suggesting that EMP1 acts as a tumor suppressor." (PMID 31652725, 2019). "This is the first study to provide evidence that the transmembrane protein EMP1 potentiates tumor metastasis in a mouse model via an underlying mechanism of Rac1 activation that in turn is responsible for promoting the invasive migration of cancer cells." (PMID 29867202, 2018). "EMP1 (5.33-fold increase) encodes a potential tumor suppressor that is associated with cellular proliferation and metastasis." (PMID 24161199, 2013). "Moreover, tumor cells with elevated EMP1 demonstrated heightened ARS risk, aging propensity, invasive and migratory capabilities, proliferative capacity, and PI3K/AKT pathway activity." (PMID 40612666, 2024). "In these tumor entities loss of EMP1 expression correlates with poor prognosis." (PMID 31450568, 2019). "The expression level of EMP1 was significantly positively correlated with the fibroblast infiltration level, tumor microenvironment score, and stromal cell score." (PMID 40016223, 2025). "The average Log2 (TPM + 1) expression level (TPM, transcripts per million) of EMP1 in the Normal group was 2.788 ± 1.279, while in the Tumor group, it was 2.858 ± 1.131." (PMID 39866225, 2025). "The results showed that EMP1 expression was positively correlated with the tumor microenvironment score, stroma score, and the infiltration of macrophages, endothelial cells, and fibroblasts." (PMID 40016223, 2025). "COL1A1 and EMP1 were significantly upregulated in tumor tissues, while MYH11 and SASH1 were significantly downregulated." (PMID 41099090, 2025). "This provided a molecular theoretical basis for the design of drugs that inhibit the activation of the TGF-β/Smads pathway in tumor cells by modulating the function of the EMP1-VASP axis." (PMID 41285728, 2025). "Consistent with a tumor suppressor role, EMP1 overexpression significantly inhibited proliferation, whereas EMP1 knockdown enhanced proliferative capacity." (PMID 41458590, 2025).
tumor (continued). "Subcutaneous tumor-bearing and tail vein metastasis experiments in nude mice were performed in nude mice to investigate the effect of EMP1 knockdown on the growth of xenograft tumors and the hematogenous metastasis of TNBC cells." (PMID 40016223, 2025). "High expression signals for EMP1 were prominently localized at the tumor-stroma interface, particularly concentrated in the Differentiated/Keratinizing Tumor and Metabolic/Secretory Tumor regions that directly abut the Fibrotic Stroma." (PMID 41099090, 2025). "In our tumor epithelial dataset, genes with the strongest positive correlation with TM4SF1 expression within the HV tumor cells were EMP1, CLDN4, EZR, and KRT19." (PMID 40527915, 2025). "Mechanistically, EMP1 suppresses tumor progression by inhibiting cell proliferation, invasion, and migration through modulation of the PI3K/AKT signaling pathway." (PMID 41458590, 2025). "The results revealed a significant positive correlation between the expression of METTL3 and IGF2BP3 and EMP1 in tumor cells." (PMID 41285728, 2025). "Building on our in vitro findings, we validated the tumor-suppressive role of EMP1 in TNBC using an in vivo xenograft model." (PMID 41458590, 2025). "EMP1 overexpression robustly curbed tumor growth, as evidenced by reduced tumor volume and weight compared to control groups." (PMID 41458590, 2025). "Current studies on EMP1 mainly focus on tumor invasion, with its molecular function remaining controversial." (PMID 41284206, 2025). "In the current study, as a downstream target regulated by METTL3-IGF2BP3, EMP1 is a multiple transmembrane protein that can communicate information with the tumor microenvironment." (PMID 41285728, 2025). "Transwell invasion assays confirmed that overexpression of EMP1 bolstered the invasive capacity of tumor cells, whereas its downregulation attenuated this ability." (PMID 40612666, 2024). "Further GSEA analysis indicated that high EMP1-expressing tumor cells were significantly enriched in aging (NES = 1.58, p = 0.001), focal adhesion (NES = 1.821, p < 0.001), and PI3K/AKT/mTOR pathways (NES = 1.522, p = 0.001)." (PMID 40612666, 2024). "This study established an aging-based prognostic model for PC and identified EMP1 as an oncogenic factor that promotes EMT in tumor cells during the aging process of resectable PC patients." (PMID 40612666, 2024). "During the in vivo assessments, EMP1 attenuation manifested a pronounced decrement in the metrics of subcutaneous tumor xenografts, both in terms of volume and mass." (PMID 40612666, 2024). "In essence, this research formulated an aging-centric prognostic model for postoperative PC and pinpointed EMP1 as an oncogenic factor facilitating tumor cell EMT during the aging trajectory in resectable PC patients." (PMID 40612666, 2024). "The messenger RNA (mRNA) levels of these genes in the TCGA-GTEx cohort displayed that SPOCK2, LIPH, RARRES3, and EMP1 were significantly higher in tumor samples than in control tissues." (PMID 38535087, 2024). "Among these gene/subgroup combinations, there was increased expression of EMP1 in tumor cells compared to other cells in osteoblasts and endothelial cells." (PMID 38187400, 2023). "In SKOV3/DDP tumors, downregulation of EMP1 expression inhibited tumor growth and reduced cisplatin resistance of tumor cells." (PMID 36708070, 2023). "In vivo experiments showed that EMP1 overexpression promoted tumor growth and enhanced cisplatin resistance of tumor cells, whereas silencing EMP1 expression inhibited tumor growth and reduced tumor cell resistance to cisplatin." (PMID 36708070, 2023). "Functions mediated by the verified upregulated interferon-induced protein with tetratricopeptide repeats (IFIT) and the downregulated epithelial membrane protein 1 (EMP1) are in line with the tumor suppressive function of INPP4B seen in RB cells." (PMID 36993823, 2023).
tumor (continued). "The tumor weight and volume were significantly higher in the EMP1 group than in the NC group (p = 0.0003, p = 0.0043)." (PMID 36708070, 2023). "In SKOV3 tumors, upregulation of EMP1 expression accelerated tumor growth and enhanced cisplatin resistance." (PMID 36708070, 2023). "Of note, Emp1-TOMhigh tumor buds and micrometastases were labeled with EPCAM and E-CADHERIN, implying that they retained an epithelial organization." (PMID 36352230, 2022). "TOM expression in dissociated epithelial tumor cells measured by flow cytometry revealed heterogeneity in Emp1 expression." (PMID 36352230, 2022). "CRCs generated by implantation of AKP MTOs in the caecum also exhibited Emp1-TOMhigh invasion fronts and tumor buds that overexpressed HRC-marker genes." (PMID 36352230, 2022). "EMP1 has moved into the limelight in these tumor entities, where its expression is controversial in multiple cancer types; however, its expression and function are contradictory." (PMID 35432717, 2022). "Similar to PMP22, EMP1 has different mRNA and protein levels in diverse cancers and is involved in tumor cell proliferation, invasion, metastasis, and epithelial-mesenchymal transformation (EMT)." (PMID 36217151, 2022). "Emp1-TOMhigh cells were largely enriched at tumor buds which, in contrast, contained few Lgr5-EGFP+ cells." (PMID 36352230, 2022). "Epithelial membrane protein 1 (EMP1) is encoded by the peripheral myelin protein (PMP22) family and is also known as a tumor-associated membrane protein." (PMID 35432717, 2022). "In most cancers, the tumor suppressive functions of EMP1 have been described as inhibition of cell growth and metastasis by induction of apoptosis and prevention of angiogenesis." (PMID 35432717, 2022). "Our data suggest that decreased EMP1 expression is significantly related to increased tumor size in NSCLC." (PMID 33799364, 2021). "The correlation between EMP1 and immune cell (i.e., neutrophil, regulatory T cell) infiltration in BC tumor tissues has also been discovered by previous studies, but the exact role of EMP1 in BC tumor immunity is still unclear." (PMID 34905506, 2021). "The results showed that lower expression of EMP1 was significantly correlated with tumor size in primary lung tumors (p = 0.004)." (PMID 33799364, 2021). "Tumor tissues from non-small cell lung cancer (NSCLC) patients contain higher levels of EMP1 mRNA than the benign tissues." (PMID 31652725, 2019). "EMP1 has been shown to be regulated by miR-34a in RB cell lines and is supposed to be a potential biomarker for tumor diagnosis and prognosis of several cancers." (PMID 31450568, 2019). "The inoculation of LNCaP cells overexpressing EMP1 in the prostate glands of nude mice promotes tumor metastasis to the lymph nodes and lungs, while control LNCaP cells do not metastasize." (PMID 31652725, 2019). "In most cancers, tumor suppressive functions for EMP1 have been described like inhibition of cell growth and metastasis by induction of apoptosis and prevention of angiogenesis." (PMID 31450568, 2019). "All RB cell lines except for Rbl13 and all primary patients’ tumor samples analyzed exhibit higher endogenous miR34a expression levels and lower EMP1 expression levels compared to a healthy human retina pool." (PMID 31450568, 2019). "Decreased expression of EMP1 was also significantly correlated with tumor invasion, metastasis, clinical stage and histological grade of patients." (PMID 29416636, 2018). "Although EMP1 is reportedly downregulated in the cancer region as compared with the adjacent normal epithelium at the primary tumor site, this molecule has also been proposed as a marker of resistance to cancer therapies and related to poor prognosis." (PMID 29867202, 2018). "Activation of the PI3K/Akt pathway by EMP-1 in NSCLC cells or by EMP-3 in HCC cells in the current study promoted tumor aggressiveness." (PMID 26472188, 2015).
tumor (continued). "Apoptosis or tumor-related genes including, c-myc, Emp-1, bax, and bcl-2, play important roles in cell cycle progression, apoptosis, and cellular transformation." (PMID 26253141, 2015). "In contrast, the expression levels of c-Myc target genes encoding proteins involved in cell proliferation (i.e. EMP1, HMMR) are more expressed in the stationary core subpopulations of GBM specimens as compared to their matched tumor rim." (PMID 23967279, 2013). "EMP1 is expressed not only in normal tissues, but also aberrantly in malignant tumor tissues." (PMID 41458590, 2025). "In addition, we also observed a similar phenomenon in xenograft tumors: NF-κB1 was downregulated, while IκBα protein was upregulated in the xenograft tumor formed by the EMP1 knockdown TNBC cells." (PMID 40016223, 2025). "Therefore, further studies are required to clarify the roles of EMP1 in the context of liver and non-neoplastic diseases." (PMID 41284206, 2025). "In summary, our findings suggest that EMP1 plays a biological role as a tumor suppressor in TNBC." (PMID 41458590, 2025). "Further analyses showed that EMP1 might promote tumor invasion and metastasis via EMT and focal adhesion (FA)." (PMID 38542388, 2024). "Indeed, targeting EMP1+ cells effectively prevented tumour recurrence after surgery in preclinical models." (PMID 39443302, 2024). "Given that the majority of research agree that EMP1 can enhance tumor growth, invasion, and migration, we hypothesize that EMP1 could also promote activated HSC proliferation and migration following injury." (PMID 37008256, 2023). "Therefore, our study results demonstrated that EMP1 is a tumor promoter and is involved in cisplatin resistance." (PMID 36708070, 2023). "The accession number for gene expression sequencing experiments reported in this paper are GEO: GSE190055 (Arrays Emp1-high vs Emp1-low AKTP tumor cells), GSE208139 (Arrays MTOs co-cultured with fibroblasts), GSE207974 (RNAseq chemotherapy) and GSE207668 (RNAseq CTOs)." (PMID 36352230, 2022). "Lower expression of EMP1 was significantly related to tumor size (p = 0.004)." (PMID 33799364, 2021). "Studies have found that EMP1 serves as a tumor suppressor in multiple carcinomas." (PMID 33714198, 2021). "In NSCLC, EMP1 was associated with clinical resistance of gefitinib, EMP2 gene silencing resulted in activation of ERK and JNK in NSCLC cells, and EMP3 expression was significantly lower in tumor tissues compared to healthy lung tissues." (PMID 33799364, 2021). "Moreover, the implantation of EMP1-knockdown P3 glioma cells in athymic nude mice showed remarkably smaller tumor formations than that of control cells." (PMID 31652725, 2019). "In order to show the tumor inductive potential of EMP1 in RB cells, we additionally overexpressed EMP1 in Y79 cells expecting to see the opposite effects following TFF3 overexpression, namely higher cell viability and proliferation levels as well as decreased cell death levels." (PMID 31450568, 2019). "To investigate whether EMP1 influences RB cells’ tumor growth, we used the chicken chorioallantoic membrane (CAM) as an in vivo model." (PMID 31450568, 2019). "Photo-documentation of the tumors developing from Y79 cells inoculated onto the CAM and quantification of tumor size, weight and volume revealed that EMP1 overexpressing RB cells develop significantly larger tumors than control cells, exhibiting higher weights and volumes." (PMID 31450568, 2019). "We next evaluated the tumor-forming ability of EMP1 in vivo." (PMID 29867202, 2018). "In line with above studies, ZNF750 up-regulated the EMP1 may reduce the tumor cell invasion and metastasis." (PMID 29416636, 2018). "In contrast, we detected only three genes—CD226, Fhit, and Emp1—whose hypermethylation correlated with underexpression, suggesting that most of the cancer-specific hypermethylation has little effect on gene expression and tumor progression." (PMID 27690235, 2016).